BCL2 (BCL2 apoptosis regulator)
Diseases named in the same sentence as BCL2 in open-access papers (continued):
Sharing a sentence is not in itself a finding about the gene and the disease.
cancer (continued). "It has been found to interfere with the PI3K/Akt and Wnt/β-catenin signaling pathways, that are essential for survival and metastasis of cancer cells and key apoptosis proteins (Bax and Bcl-2)." (PMID 40417209, 2025). "It has been discovered that miR-34a, miR-34b, and miR-34c show low expression levels in cancer cells MiaPaCa2 and BxPC3, which have elevated levels of target genes Bcl-2 and Notch1/2." (PMID 40699746, 2025). "This modulation leads to an increased Bax/Bcl-2 ratio, triggering cell shrinkage, the activation of caspase cascades, and the release of cytochrome c, collectively promoting apoptosis in cancer cells." (PMID 40981159, 2025). "Cancer cells often show overexpression of anti-apoptotic proteins, like Bcl-2 and Bcl-xl, which are critical for evading the normal process of programmed cell death." (PMID 41195268, 2025). "At the same time, a favorable regulation of apoptotic proteins was observed: levels of pro-apoptotic Bax protein and cleaved PARP increased, while anti-apoptotic proteins Bcl-2 and Bcl-xL decreased, favoring the programmed death of cancer cells." (PMID 40282445, 2025). "The direct binding of quercetin to BCL-2 family proteins can trigger pro-apoptotic activity, which is particularly relevant given that anti-apoptotic BCL-2 members are often overexpressed in various cancers, making them attractive therapeutic targets." (PMID 41465610, 2025). "ABT-199 (venetoclax), a specific Bcl-2 inhibitor, has been shown to be effective as a single agent and combined with other therapies in different cancer types, including hematologic neoplasms such as leukemias and lymphomas." (PMID 40723174, 2025). "In summary, miR-205 directly targets and modulates the expression of the anti-apoptotic protein BCL-2 in multiple cancer types, thereby regulating intrinsic apoptotic pathways." (PMID 41001034, 2025). "miR-16 is known to attenuate the antiapoptotic protein B-cell lymphoma 2 (Bcl-2), whereas let-7 suppresses Rat sarcoma proteins (Ras) activity in cancer cells." (PMID 41226811, 2025). "BCL-xL and BCL-2 (anti-apoptotic proteins) were shown to be more abundant in cancer cell lines treated with chemotherapeutic drugs and bisphenol A." (PMID 41007319, 2025). "It has been reported that sIL-24 induces apoptosis in the mitochondrial pathway by increasing the protein ratio of Bax/Bcl-2, increasing cytochrome C release, and up-regulating the expression of Caspase-9 and Caspase-3 in cancer cells." (PMID 40243937, 2025). "A contrasting effect of Bcl-2 that elevates cellular levels of ROS has been documented in HL-60 cells lacking glutathione, as well as in bacteria, astrocytes, various cancer cell lines, and fibroblasts." (PMID 40867920, 2025). "For instance, exosomes loaded with Bcl-2 inhibitors can re-sensitize cancer cells to apoptosis by negating the anti-apoptotic effects of Bcl-2 proteins." (PMID 40843170, 2025). "By strategically advancing our understanding and targeting of the proteasome-Bcl-2 axis, we can unlock transformative strategies, leading to more effective and durable treatments for a wide range of cancers." (PMID 40841912, 2025). "In many types of cancer, anti-apoptotic proteins, such as Bcl-2, are overexpressed, leading to resistance to cell death." (PMID 39861761, 2025).
cancer (continued). "Further experiments found that IL‐17 secreted from γδT‐17 cells increased the expression of an anti‐apoptotic protein BCL‐2, which can promote radioresistance of cancer cells." (PMID 39901895, 2025). "For instance, both SnCs and many cancer cells rely on the anti-apoptotic B-cell lymphoma-2 (BCL-2) family of proteins (BCL-2, BCL-xL, and MCL-1) for their survival." (PMID 41614753, 2025). "PNAs have been functionalized onto adenoviral vectors to target G-Quadruplex structures in the Bcl-2 oncogene, a key regulator of apoptosis and cancer progression, supporting their application in anticancer gene therapy." (PMID 40286158, 2025). "This newly understood mechanism positions ARTS and its interaction with XIAP and Bcl-2 as promising targets in the development of next-generation therapies for cancers resistant to conventional treatments." (PMID 40841912, 2025). "The results of the Western blot analysis showed that, in the A-549 cancer cell line, the leaf extract induced the expression of the Bax protein and decreased the expression of Bcl-2." (PMID 39940708, 2025). "Realizing that priming state indicates a cancer’s dependency on one or another of the BCL-2 proteins for their survival, this information can be exploited therapeutically." (PMID 40507334, 2025). "Its modulation of the Bax/Bcl-2 ratio suggests a mitochondrial apoptotic mechanism, as noted in cancer but less understood in normal reproductive tissues." (PMID 40746732, 2025). "In this regard, studies have shown that, even without a significant increase in BAX, the reduction in BCL-2 expression can be sufficient to destabilize the mitochondrial membrane potential, especially in cancer cells dependent on BCL-2 for survival." (PMID 40126263, 2025). "These nanoparticles were loaded with ABT-737, a Bcl-2 inhibitor, exploiting Bcl-2 blockade as a potential therapeutic strategy against this highly aggressive cancer." (PMID 41155958, 2025). "Over-expression of oncoproteins Bcl-2 and Mcl-1 led to the evasion of cancer cell apoptosis and promoted cancer cell survival." (PMID 40141366, 2025). "Several prior reports have focused on polymorphisms in the genes encoding BCL‐2, caspase‐3, caspase‐9, and NKX3‐1, and their relevance to cancer treatment." (PMID 40344485, 2025). "BCL2 expression is elevated in hypoxia compared to normoxia due to molecular and cellular adaptive mechanisms that support cancer cell survival." (PMID 40539846, 2025). "As a result, the overactivation of Akt promotes cell survival by enhancing Bcl-2 activity and inhibiting Bax, both of which play crucial roles in cancer cell resistance." (PMID 40283879, 2025). "Bcl-2 can resist cell apoptosis, while Bax can antagonize the protective effect of Bcl-2 on cancer cells." (PMID 40606986, 2025). "Studies have shown that osthole, a natural furanocoumarin, induces apoptosis in cancer cells by activating caspases and modulating Bcl-2 and Bax proteins, which regulate mitochondrial membrane permeability." (PMID 40430886, 2025). "The BAX and BCL2 genes are also involved in the regulation of apoptosis, which is a key process in the development and progression of cancer." (PMID 41203700, 2025). "The LE also drastically reduced the expression of anti-apoptotic genes Bcl-2 and Bcl-xL in cancer cells." (PMID 41465738, 2025). "Substantial evidence highlights the regulatory effects of phytochemicals on Bax/Bcl-2/caspase-3 signaling in cancer." (PMID 40371330, 2025). "BCL-2 in particular helps cancer cells avoid cell death, so drugs targeting BCL-2 are being explored in SCLC." (PMID 41194225, 2025). "BamH1 A fragment leftward reading frame 1 (BALF1) plays a role in maintaining Bcl-2 protein with anti-apoptotic characteristics stability, leading to cancer progression." (PMID 40052129, 2025). "This potential is evidenced by its ability to modulate the expression of the pro-apoptotic gene BAX and the anti-apoptotic gene BCL-2, thereby inducing apoptosis in cancer cells." (PMID 39918669, 2025).
cancer (continued). "Increased expression of BCL2 family members including MCL1, BCL2L1 (BCL-xL), BCL2A1 (BFL1), and BCL2 itself drives resistance to single-agent venetoclax in various cancers." (PMID 39894894, 2025). "A cell-permeable stabilized version of this peptide, BCL2/IP3R disrupter-2 (BIRD-2), has been applied in different BCL2-dependent cancer cell types." (PMID 40113751, 2025). "BCL2 is a protein that plays a key role in controlling cell death, which is important for normal body functions but can also contribute to cancer." (PMID 40136517, 2025). "KS18 also demonstrated greater cancer cell death than the Bcl-2/Bcl-xL inhibitors venetoclax and ABT-737, further highlighting Mcl-1 as a dominant survival factor in resistant MM." (PMID 41149606, 2025). "Venetoclax, a selective Bcl-2 inhibitor, binds to Bcl-2 and blocks its antiapoptotic activity, inducing apoptosis in cancer cells." (PMID 40141030, 2025). "Drugs like venetoclax, which focuses on intrinsic apoptotic pathways, are already in use, and BH3-mimetics that directly provoke apoptosis by inhibiting pro-survival BCL-2 proteins are now in clinical testing as cancer therapies." (PMID 39946620, 2025). "Gene expression analysis revealed upregulation of pro-apoptotic genes (BAX, Caspase 3, and Caspase 9) in cancer cells, alongside a decrease in anti-apoptotic BCL-2 expression." (PMID 39805861, 2025). "Members of the BCL‐2 gene family, for example, are well established as important regulators of apoptotic death, with BCL‐2 overexpression contributing to the development of this cancer type." (PMID 40344485, 2025). "To assess the functional activity of our evolved DNAzymes in a cellular context, we evaluated the expression of BCL-2 mRNA in multiple cancer cell lines following DNAzyme treatment." (PMID 40643466, 2025). "Many cancers exploit anti-apoptotic BCL-2 proteins—like BCL-2, BCL-XL, and MCL-1—to evade cell death." (PMID 40204952, 2025). "Studies have indicated that biochanin A promotes apoptosis by inhibiting the Akt and MAPK pathways, reducing NF-κB activity, and modulating the Bcl-2/Bax ratio, demonstrating anti-cancer effects in breast and prostate cancers." (PMID 41153768, 2025). "Elevated Bcl-2 protein levels are frequently observed across multiple cancer types, making Bcl-2 antagonists promising anti-cancer therapies." (PMID 40841912, 2025). "The landmark discovery of the BCL-2 gene and then its function marked the identification of inhibition of apoptotic cell death as a crucial novel mechanism driving cancer development and launched the quest to discover the molecular control of apoptosis." (PMID 40204952, 2025). "Their specific involvement and prominence in driving Bcl-2 expression can vary depending on the cancer type and its molecular subtypes." (PMID 40841912, 2025). "Their experiments, conducted on cell cultures, showed that the presence of scopoletin leads to the inhibition of the expression of genes responsible for the development of cancer, such as Bcl-2 and c-Myc." (PMID 40430886, 2025). "Both treatment doses elevated the Bax/Bcl-2 ratio and reduced the expression of cancer stem cell markers CD44, EpCam, and VEGF compared to controls." (PMID 40371330, 2025). "B cell lymphoma 2 family (BCL2) gene activation, which promotes carcinogenesis through BCL2-mediated apoptosis, is a frequent sign of cancer." (PMID 41007319, 2025).
cancer (continued). "We document the usefulness of this feature by comparing PLIP interactions of the cancer drug venetoclax with the native protein–protein interaction of Bcl-2 and BAX." (PMID 40347107, 2025). "Activation of Caspase-3/9 and upregulation of the Bax/Bcl-2 ratio promote mitochondrial-dependent cancer cell apoptosis." (PMID 40584613, 2025). "For instance, guanidinium-functionalized compounds have been shown to target the G-quadruplex within the promoter region of the BCL-2 gene, a key regulator in cancer development." (PMID 41226615, 2025). "Some BCL2 members can effectively inhibit programmed apoptosis in cells and then induce malignant tumors." (PMID 39735667, 2025). "Reducing Bcl-2 levels or increasing Bax levels can stimulate the process of apoptosis in a variety of cancer cells." (PMID 40839202, 2025). "Molecular docking revealed stronginteractions of sarcorine C and salonine C with key cancer-associatedproteins (CDK2, KRAS, CYP17A1, Bcl-2, MMP-2, and NOS)." (PMID 41141772, 2025). "As anti-apoptotic BCL2 also operates as an inhibitor of IP3R channels, strategies to disrupt IP3R/BCL2 complexes in cancer cells have been investigated." (PMID 40113751, 2025). "The efficiency of the different studied extracts against the activities of caspase-3 and Bcl-2 enzymes was evaluated in the three studied cancer cell lines (HepG-2, Caco-2, and A549)." (PMID 40284441, 2025). "Overall, with respect to the dosage schemes of the different drugs, the most effective drug to reduce the viability of T-PLL cancer cells was venetoclax (BCL2 inhibitor inducing apoptosis), which was tested for both analyzed T-PLL cohorts." (PMID 41146244, 2025). "Treatment with garlic led to an increased expression of tissue transglutaminase, a protein involved in the activation of apoptosis, while the Bcl-2, which inhibits cell death and promotes cancer cell survival, was significantly reduced." (PMID 40282445, 2025). "In this study, a known cancer target, BCL2, in complex with partner proteins was explored to highlight the multifaceted role of BCL2 in regulating cell survival and cell death." (PMID 40136517, 2025). "Unlike typical oncogenes that drive cell proliferation, these scientists found that BCL-2 prevented cell death; its anti-apoptotic function allowed cancer cells to survive despite violating cellular checkpoints." (PMID 40204952, 2025). "This study focused on understanding how BCL2 interacts with partner proteins and how these interactions influence cancer progression and resistance to treatments." (PMID 40136517, 2025). "In cancer, most malignancies retain dependence on one or more anti-apoptotic BCL2 proteins and these therefore are prime candidates for therapeutic targeting." (PMID 40113751, 2025). "In breast cancer, Gal-3 can bind to Bcl-2 to initiate anti-apoptotic functions and enhance metastatic potential, as well as promote cancer progression through binding and activating K-Ras." (PMID 40134029, 2025). "According to numerous studies, overactivation of Akt stimulates Bcl-2 while inhibiting Bax, thereby promoting cancer cell survival." (PMID 40052129, 2025). "For example, nisin has shown a cytotoxic effect on the SW480 cancer cell line, inducing apoptosis by increasing the ratio of bax/bcl-2 on both mRNA and protein levels." (PMID 38748307, 2025). "In these cancers, it suppresses Bcl-2 indirectly through angiogenesis inhibition or directly through the JNK pathway, thereby inducing apoptosis." (PMID 41153768, 2025). "In various cancer cells, the Gal-3 and Bcl-2 interaction influences mitochondrial apoptosis, providing resistance to agents that induce apoptosis." (PMID 40134029, 2025). "Since then, numerous studies have shown that alterations in the expression of Bcl-2 proteins, such as Bcl-2 and Bax, are frequently observed in various types of cancer." (PMID 40227591, 2025).
cancer (continued). "Since the increase in the Bax/Bcl2 ratio also induces mitochondria damage in cancer cells, leading to autophagic cell death via a caspase‐3‐independent manner." (PMID 39607347, 2025). "The mechanistic details of cancer cell death in response to combination treatment of the pro-apoptotic BCL2-specific inhibitor Venetoclax and HMAs remain to be investigated, possibly with the help of the novel drug GSK5032." (PMID 40611304, 2025). "Further, (S,R)-4v markedly reduced the protein level of Bcl-2, which is a critical downstream target of the NF-κB pathway and closely related to the progression of cancers." (PMID 40683874, 2025). "Marinopyrrole A, a marine-derived natural product, exemplified this potential by inducing proteasomal degradation of Mcl-1, thereby sensitizing resistant cancer cells to Bcl-2 inhibitors and TRAIL-based therapies." (PMID 41149606, 2025). "One study demonstrated that Celastrus orbiculatus extract (COE) upregulates the expression of pro‐apoptotic proteins BAX and Cleaved‐Caspase‐3 while downregulating anti‐apoptotic proteins Bcl‐2 and Bcl‐xL in cancer cells." (PMID 41231037, 2025). "Cancer cells often evade cell death by amplifying the expression of anti-apoptotic proteins, such as B-cell lymphoma 2 (BCL2)." (PMID 40382494, 2025). "Accumulating evidence shows that venetoclax is a highly selective and effective BCL‐2 inhibitor that can restore the apoptotic potential of cancer cells." (PMID 40062510, 2025). "Our study presents a novel and effective strategy for the in vitro evolution and characterization of trans-acting RNA-cleaving DNAzymes specifically targeting the BCL-2 mRNA—a key anti-apoptotic gene that is overexpressed in many human cancers." (PMID 40643466, 2025). "This cascade of events promotes apoptosis by reducing Bcl-2 and lessens the invasive potential of cancer cells by inhibiting NF-κB and MMP-9, suggesting a promising therapeutic role for apigenin." (PMID 41226811, 2025). "A higher level of overall priming paralleled a higher sensitivity of competent TIS cancer cells to BCL-2/BCL-xL- and BCL-xL-targeted inhibitors when comparing TIS phenotypes among themselves." (PMID 40055336, 2025). "Bax and Bcl-2 expression further confirmed this apoptotic induction in lupeol-treated lung cancer A427 cancer cells." (PMID 40417209, 2025). "BCL‐2 inhibitors are also in widespread use in other hematological malignancies, and a specific PP2A inhibitor, LB‐100, is currently in use for solid oncology tumors, undergoing a phase 1b/2 clinical trial (NCT03886662)." (PMID 40124717, 2025). "They worked by turning down a protein that helps cancer cells survive (Bcl2), boosting one that promotes cell death (caspase 8), and pushing more cancer cells into a stage where they die." (PMID 41283276, 2025). "This cap-independent translation mechanism permits cancer cells to produce key survival proteins, such as BCL2, XIAP, and NRF2, which are essential to block cell death, resist chemotherapy, and adapt to stressful conditions." (PMID 40940829, 2025). "BCL2, an anti-apoptotic protein, plays a crucial role in the regulation of cell survival, and its expression is often dysregulated in various cancers, contributing to tumorigenesis and the resistance of cancer cells to cell death signals." (PMID 41551597, 2025).